IFI30 (IFI30 lysosomal thiol reductase)
Diseases named in the same sentence as IFI30 in open-access papers (continued):
Sharing a sentence is not in itself a finding about the gene and the disease.
cancer (29 papers, 2013 to 2025). A tumor composed of atypical neoplastic, often pleomorphic cells that invade other tissues. "The main pathways significantly associated with IFI30 in pan-cancer are “Interferon gamma response, Interferon alpha response”, “inflammatory response, allograft rejection”, and “complement pathway activation”." (PMID 39925804, 2025). "Based on the differential expression of IFI30 in pan-cancer, a GSEA on Hallmarks was performed on 20 cancer types to identify the underlying features of IFI30-associated cancers." (PMID 39925804, 2025). "Therefore, further research is warranted to elucidate the function and underlying mechanisms of IFI30 in different cancers, aiming to determine its viability as a diagnostic and prognostic biomarker or as a therapeutic target." (PMID 40186402, 2025). "The other two genes, NCF2 and IFI30, play roles in immune response, antigen presentation, inflammation, cell invasion, and cell survival, and they have been considered as diagnostic and prognostic biomarkers in several cancers." (PMID 37685875, 2023). "Dysregulated expression of IFI30 has been associated with human cancers." (PMID 37784035, 2023). "Therefore, IFI30 can be used as a diagnostic and prognostic biomarker in cancers." (PMID 35910561, 2022). "Based on the coupled analyzes of TCGA and GTEx data, we comparatively compared the IFI30 expression in 33 cancers that are currently in common use." (PMID 39925804, 2025). "It is worth mentioning that the most significant of the five segments was MHC-related genes, and at the pan-cancer dimension, IFI30 showed significant positive correlations with MHC-related genes in different malignancies, except for ALL as well as DLBC." (PMID 39925804, 2025). "Gene Set Enrichment Analysis (GSEA) findings indicated that IFI30 was highly involved in immunomodulatory and inflammation-related pathways in almost every cancer type." (PMID 39925804, 2025). "Data from the GEPIA2 database showed that, compared with normal tissues, IFI30 mRNA was generally elevated in 18 different cancers, including ESCA." (PMID 40186402, 2025). "In conclusion, our study comprehensively depicts the immunotherapeutic properties of IFI30 at the pan-cancer level, a fact that shall provide fresh orientations for immunotherapy." (PMID 39925804, 2025). "Increased IFI30 expression has been shown to enhance the ability of immune cells to eliminate various cancers by promoting the antigen presentation process." (PMID 39308856, 2024). "Pan-cancer analysis revealed that IFI30 is highly expressed in most human tumors compared with normal tissue." (PMID 38517387, 2024). "The present study gives a new insight into the role of IFI30 in vascular development and provides potential strategies for cancer treatment." (PMID 35910561, 2022). "The expression levels of PLXNB1, PTK2, and IFI30 in the cancer group were lower than those in the normal group." (PMID 36211454, 2022). "Recent studies showed that IFI30 played an important role in the immune response of malignant tumors." (PMID 34400904, 2021). "Systematic pan-cancer analysis of IFI30 by combining transcriptomic as well as single-cell sequencing data in the current study might to a certain extent point the way to such a puzzle." (PMID 39925804, 2025). "Despite its recognition in cancer immunotherapy, IFI30 remains a nascent focus." (PMID 39925804, 2025). "IFI30 has been documented to exhibit diverse roles across various cancer types." (PMID 40186402, 2025). "The significant differential expression could be at least somewhat suggestive of an important role of IFI30 in pan-cancer." (PMID 39925804, 2025). "However, in similarity to the significant correlation of DC, Macrophage equally had a significant correlation with IFI30 in pan-cancer." (PMID 39925804, 2025). "Finally, we performed a comprehensive pan-cancer analysis on IFI30, which was identified as having the highest HR value among the model genes." (PMID 38517387, 2024).
cancer (continued). "Previous studies have indicated that IFI30 plays a protective role in human cancers." (PMID 37408388, 2023). "The current consensus that inflammatory responses, TNFA signaling, and IFN signaling correlate with immunotherapy in cancer and patient response implies that the potential immunotherapeutic value of IFI30 could be explored through these pathways, which also substantiates our previous hypothesis." (PMID 39925804, 2025). "The top three cancer types were, GBM, LGG, and KIRP, which were close to the immune infiltration results implied by EPIC, suggesting an overwhelming presence of IFI30 in the immune microenvironment of these three cancers." (PMID 39925804, 2025). "Similarly, vital immune checkpoint genes such as HAVR2, CD274, CTLA4, ITGB2, ICAM1, CCL5, CXCL10 all exhibited robust correlation with IFI30, and this immunotherapy might, in the future, establish a bond with IFI30, bringing new opportunities for cancer treatment." (PMID 39925804, 2025). "The expression of TNFAIP3 was higher in immune cells, especially in epithelial carcinoma, macrophages, and CD8+ T‐cells (left), while TGFBI, IFI30, SPP1, and EREG were expressed more highly in macrophages than other cells." (PMID 35634956, 2022). "Although the current research on IFI30 in cancer immunotherapy is gaining momentum, the lack of depth and breadth of existing studies is a shortcoming that limits it from becoming a reliable target for immunotherapy." (PMID 39925804, 2025). "In addition, cancer infiltrating antigen-presenting cells elicit MHC II antigen processing and presentation through IFI30, shaping an antitumor T cell strategy." (PMID 30651403, 2019). "Using the Pan-Cancer TCGA dataset gathering RNA-seq data from 11,060 patients, an anticorrelation between TET2 expression and mRNA levels of lysosome proteins was confirmed for CLN3, CTSD, CTSF, CTSZ, IFI30, and NAGLU, suggesting TET2 might down-regulate lysosomal genes in various types of cancer." (PMID 35351824, 2022).
cardiovascular disease (1 paper, 2022). "Additionally, 32 TR genes (including GBP1, IFI30, CSTB, ACTR2, etc.)were found within risk loci of cardiovascular disease (Fisher’s exact test, P = 0.394)." (PMID 35133977, 2022).
neurogenetic diseases (1 paper, 2024). "Regarding cDC1s, the genes associated with MHC II antigen presentation (HLA-DRB5, IFI30), immune activation (NAPSB), and developmental and neurogenetic diseases (NBPF14) were highly expressed in active TAO compared to NCs." (PMID 38728262, 2024).
IFI30 also shares sentences with these, for which no sentence is quoted: diffuse large B-cell lymphoma (6 papers); infection (4); viral infection (3); colon cancer (2); flu (2); malaria (2); metastatic melanoma (2); abdominal aortic aneurysm (1); allergic asthma (1); Alzheimer disease (1); amenorrhea (1); asthma (1); B cell lymphoma (1); bone osteosarcoma (1); colorectal cancer (1); coronary artery disease (1); Crohn disease (1); dyslipidemia (1); eosinophilia (1); hematological malignancies (1); HIV-1 infection (1); Hyperglycemia (1); Listeria monocytogenes infection (1); liver fibrosis (1); lymphoma (1); metastatic cancers (1); nephrotic syndrome (1); ovarian carcinoma (1); Pituitary adenoma (1); posttraumatic stress disorder (1).
A further 9 diseases each share a sentence with IFI30 in 1 paper.